EEF1A1 (eukaryotic translation elongation factor 1 alpha 1)
Diseases named in the same sentence as EEF1A1 in open-access papers (continued):
Sharing a sentence is not in itself a finding about the gene and the disease.
cancer (continued). "We analyzed data from two independent groups of cancer cell lines and identified alterations in additional genes (PUM3, EEF1A1 and ELP4) that potentially increase sensitivity to olaparib." (PMID 33803939, 2021). "Further investigations of the remaining genes such as FN1, EEF1A1, COL1A1, SFTPB, SFTPC, and ATP1A1 will shed light on the identification of novel biomarker genes for a pan-cancer cohort." (PMID 31324856, 2019). "EEF1A1, EEF1A2 and EEF1D have previously been reported to be potential candidates for gene amplification, leading to observed overexpression in certain cancers." (PMID 29342219, 2018). "We found that there is a reciprocal relationship between EEF1A1 and EEF1A2 transcript levels in tumor tissues of different cancer types, indicating towards a tight regulation of any one isoform over another, in cancers also." (PMID 29342219, 2018). "These suggested eEF1A1 as a molecular marker to predict the selectivity and efficiency of 5-ALA based PDT in cancer therapy." (PMID 27150264, 2016). "Among these genes, EEF1A1, PLEC, and TCEB1 are common cancer-related genes." (PMID 35126520, 2022). "The targeting of eEF1A1 by GT75 impaired cell viability in PC-3 cancer cells but not in PZHPV-7 non-tumourigenic cells, indicating a specific role for the protein in cancer survival." (PMID 35456960, 2022). "OS remained significantly altered with differences in expression of eIF2G (p < .050) and eEF1A1 (p < .020), but not for eIF5A cancer stroma expression (p < .219) or eIF5A nuclear expression (p < .065)." (PMID 35718769, 2022). "EEF1A1 belongs to the translation factor-related class translation factor GTPase superfamily, and strongly promotes the heat shock response (HSR), thereby protecting cancer cells from proteotoxic stress (such as oxidative stress and hypoxia)." (PMID 36038612, 2022). "Taken together, our study discovered eEF1A1 as a novel photosensitizer binding protein, which may play an essential role in the enrichment of ALA-induced PpIX in cancer cells during PDT." (PMID 27150264, 2016). "Compared with PZHPV-7, cancer cells showed no major variations in EEF1A1 mRNA; eEF1A1 protein increased only in cytoskeletal/nuclear fraction." (PMID 22095224, 2012). "However, some studies suggest that EEF1A1 does not influence cell apoptosis, possibly due to differences in cancer types." (PMID 38965582, 2024). "We found lots of them might play a key role in the transformation of enterocyte progenitor cells to cancer cells such as MALAT1, B2M, EEF1A1, RPL5, B3GNT7, RHOB and ACTB might play a key role in the transformation of enterocyte progenitor cells to cancer cells." (PMID 36944972, 2023). "Indeed, more eEF1A1 were expressed in HepG2 cancer cell line than L02 noncancerous hepatic cell line, which was assessed by both quantitative reverse transcription-polymerase chain reaction (qRT-PCR) and western blotting." (PMID 27150264, 2016). "Furthermore, the prostate tumor-inducing gene 1 (PTI-1), which has oncogenic properties and is expressed in cancer, but not normal cell lines, shares significant homology with eEF1A1." (PMID 23799104, 2013). "Importantly, eEF1A1 serves as a housekeeping protein in the same tissues and seemingly is not related to the cancer in these cases." (PMID 18221514, 2008). "The fact that the high eEF1A1 levels in tumour tissue and cancer cells are not accompanied by an increase in eEF1A1 mRNA levels may be related to the fact that the eEF1A1 protein has a long half-life; similar observations have been made for the ubiquitin-like protein FAT10 in cancer cells." (PMID 35456960, 2022).
cancer (continued). "In contrast to eEF1A2, the cytoplasmic eEF1A1 did not significantly differ between non-tumourigenic and tumourigenic cells and an increase of the protein was seen only in the cytoskeletal/nuclear fraction but without significant variation between the cancer cell lines tested." (PMID 22095224, 2012). "The EIF5A-HMGN2 and EEF1A1-VIM fusion transcripts were detected and validated in all tested cell lines and both controls, indicating that these fusions were not cancer-specific." (PMID 26672768, 2016). "Curiously, in the non-tumourigenic PZHPV-7, amplification of EEF1A1 and EEF1A2 genes was detected, even though these cells that barely express EEF1A2 and EEF1A1 expression did not result to be higher than in cancer cells." (PMID 22095224, 2012).
tumor (74 papers, 2005 to 2026). "Thus, pro-apoptotic function is a possible mechanism underlying the protective effect of EEF1A1 against tumor development or progression." (PMID 31703307, 2019). "E7 protein of HPV38 has been shown to interact with both eEF1A1 and eEF1A2 proteins leading to cellular immortalization and transformation of primary keratinocytes probably through disruption of actin stress fiber formation, a critical event linked to tumor formation." (PMID 25905039, 2015). "The dysregulation of eEF1A1 is a common etiologic agent in oncogenesis and the development of tumor." (PMID 35607944, 2023). "Other 6q15 genes with potential tumor suppressive functions for example include EEF1A1, ZNF292, SNORD50A, PRDM1, CCNC, FOXO3, WISP3, and FRK." (PMID 34625909, 2022). "The eEF1A1 and eEF1A2 proteins have been suggested as possible features of cell transformation and tumour progression." (PMID 35456960, 2022). "The results revealed that EEF1A1 mRNA was decreased in tumor tissue compared to that in normal tissue." (PMID 31703307, 2019). "EEF1A1 mRNA levels were significantly reduced in the tumor tissues compared to those in the normal adjacent tissue." (PMID 31703307, 2019). "In the tissue with positive EEF1A1 immunostaining, diffuse cytoplasmic staining was observed in tumor cells." (PMID 31703307, 2019). "Cell cycle-associated EEF1A1 mRNA expression and the HSR, protecting tumor cells from stress-induced cell death, explain the opposite direction of misexpression and indicates strong post-translational control of eEF1α1 protein levels in tumors." (PMID 30224719, 2018). "Time-dependent regulation of EEF1A1 in normal and tumor tissue resulted in stable expression (≤2-fold change) of EEF1A1 in nearly all samples (N10: 17/20; N20: 18/20; N45: 19/20; T10: 18/20; T20: 17/20; T45: 13/20)." (PMID 26222051, 2015). "This study demonstrates that EEF1A1 is not only stably expressed in normal and tumor colorectal tissue but also following cold ischemia." (PMID 26222051, 2015). "In tumor tissue samples, the CV of EEF1A1 (6.12) was the second highest compared with UBC and GAPDH." (PMID 26222051, 2015). "CVs of GAPDH, UBC and EEF1A1 across ischemia time points and patients in normal and tumor colorectal tissue." (PMID 26222051, 2015). "We also examined the role of eEF1A1 in mediating TUBB2B-promoting tumor growth in vivo, and showed that overexpression of eEF1A1 could partially rescue the tumor growth in TUBB2B-depleted cells." (PMID 39962586, 2025). "In addition, EEF1A1 methylation in DMG tissues was validated through immunoprecipitation of EEF1A1 from tumor protein lysates, followed by Western blot analysis using anti-pan methyl lysine antibodies." (PMID 39954016, 2025). "The previous findings have proved that mTOR is essential for CDCA5 function in ccRCC, we thus examine whether the pro-tumor function of CDCA5/EEF1A1 was via mTOR pathway." (PMID 38658931, 2024). "GT75 is another tumor inhibitor specially interfering with eEF1A1 activity." (PMID 35607944, 2023). "Importantly, TOPK inhibitor HI-TOPK-032 suppressed the EC cell proliferation and tumor growth by TOPK/YB1/eEF1A1 signal pathway in vitro and in vivo." (PMID 37328464, 2023). "TPM3, CHMP4C, EEF1A1, FASN, TNF, S100A10, and IL1A represent a high-risk score and poor prognosis, suggesting that these genes may be associated with the tumor process in patients with CC and appear to be pro-oncogenes." (PMID 36685937, 2022). "EEF1A1 can promote tumor spread through the STAT1-cyclin D1 pathway." (PMID 35126520, 2022).
tumor (continued). "In conclusion, the LNC CRYBG3/eEF1A1/MDM2/MTBP axis is a novel signaling pathway regulating tumor metastasis and may be a potential therapeutic target for NSCLC treatment." (PMID 33809929, 2021). "Few reports have discussed the role of eEF1A1 in tumor metastasis." (PMID 33809929, 2021). "Of the total study population, EEF1A1 mRNA expression levels were investigated in 15 patients from whom fresh tumor and adjacent normal tissue could be harvested." (PMID 31703307, 2019). "We next evaluated whether EEF1A1 mRNA expression might correlate with specific clinical parameters, including tumor invasion, nodal status, metastasis, stage, age and estrogen receptor (ER), progesterone receptor (PR) and HER2 receptor status." (PMID 30224719, 2018). "Furthermore, within this study EEF1A1 was identified as a potential ischemia reference gene, both in normal and tumor colorectal tissue." (PMID 26222051, 2015). "EEF1A1 exhibited a small CV and the best correlation of ranks between normal and tumor tissue." (PMID 26222051, 2015). "Furthermore, expression of EEF1A1 was unchanged when comparing expression in normal and tumor tissue samples after resection." (PMID 26222051, 2015). "The median immunostaining intensity of eukaryotic translation elongation factor 1 alpha 1 (eEF1A1), one of the candidates identified, was significantly higher in osteoblasts in close proximity to metastatic tumour cells compared with osteoblasts in control bone (p = 0.0353, Mann Whitney U)." (PMID 22355332, 2012). "There are numerous reports of the cytoskeletal modifying properties of eEF1A1; again, these might differ from eEF1A1 to eEF1A2 and possibly relate to tumour invasion and propensity to metastasize." (PMID 17437010, 2007). "Together, these results suggested that eEF1A1 could promote CRC tumor growth in vivo." (PMID 35607944, 2023). "The eEF1A1 protein may play different roles in different tumours." (PMID 35456960, 2022). "Indeed, eEF1A1 was reported as a target for anti-tumor therapy." (PMID 27150264, 2016). "Therefore, we can infer that the antiproliferative effects of the drug in tumor cells could not only be ascribed to its selectivity towards eEF1A2, but probably to the selective role of the latter with respect to eEF1A1 in promoting oncogenic transformations." (PMID 27713531, 2016). "Thus, eEF1A1 over-expression seen in osteoblasts may occur as a response to the presence of tumour cells." (PMID 22355332, 2012). "After uptake by tumor cells, acetate upregulates glutamine and UDP-GlcNAc levels, enhancing the O-GlcNAc modification of eukaryotic elongation factor 1A1 (eEF1A1), thereby promoting tumor growth." (PMID 41355959, 2026). "A stringent cross-comparison identified five proteins (PSAP, MARCKS, eEF1A1, DDX39B, and RACK1) as consistently and differentially regulated across tumor stages." (PMID 42064067, 2026). "Overall, NEDD4L plays a crucial role in inhibiting tumor angiogenesis by regulating eEF1A1 ubiquitination and degradation, providing new insights into the NEDD4L-eEF1A1 axis and its potential as a therapeutic target." (PMID 40567051, 2025). "The EEF1A1 gene is known to interact with the FBXO32 gene to promote PDAC progression and contribute to tumor growth and metastasis." (PMID 39688793, 2025). "IHC analysis of the tumor in nude mouse tumors showed that UCHL3 overexpression increased EEF1A1 protein level, while UCHL3 inhibition downregulated EEF1A1 protein level." (PMID 38965582, 2024). "UCHL3 and EEF1A1 formed a functional axis in facilitating the malignant progression of HCC, proving new insights for the anti-tumor targeted therapy for HCC." (PMID 38965582, 2024). "We classified UM tumor cells into six distinct subclusters based on marker gene expression: C0 WSB1+ TCs, C1 EEF1A1+ TCs, C2 HSPB7+ TCs, C3 XIST+ TCs, C4 GNG11+ TCs, and C5 PCOLCE+ TCs." (PMID 39635521, 2024). "The combined expression score for all tumours (EOC and BL) in eEF1A1, eIF2α, eIF5B and eIF6 nuclear expression was equal (CS = 0)." (PMID 35718769, 2022).
tumor (continued). "Examination of TCGA dataset revealed overexpression of all the translation elongation factors being studied, except EEF1A1 which was downregulated and EEF2, which didn’t show any significant difference in expression between the tumor and normal groups." (PMID 29342219, 2018). "TCGA analysis further confirmed that mRNA levels of EEF1A1, EEF1A2, EEF1B2, EEF1G and EEF2 were significantly downregulated in tumor tissues than normal." (PMID 29342219, 2018). "Therefore, UCHL3 and EEF1A1 jointly promote the migration, stemness, and drug resistance of HCC cells, as well as influencing the growth of mouse tumor models." (PMID 38965582, 2024). "Moreover, overexpressed TOPK promoted cell proliferation and tumor growth of EC cells in vitro and in vivo by YB1/eEF1A1 signal pathways." (PMID 37328464, 2023). "Collectively, these results suggested that eEF1A1 was remarkedly increased in CRC and may play tumor promoting role in CRC." (PMID 35607944, 2023). "In most of the datasets, EEF1A1 mRNA levels were significantly decreased in tumor as opposed to normal tissues." (PMID 29342219, 2018). "Corresponding m/z from collagen type I alpha 2 (COL1A2), cathepsin (CTSG), elongation factor 1-alpha 1 (EEF1A1), EH domain-containing protein 2 (EHD2), epiplakin 1 (EPPK1), prelamin-A/C (LMNA), and prolargin (PRELP) showed higher intensity distribution in HND in comparison to LND tumour areas." (PMID 40603632, 2024). "EEF1A1 may be predictor of good prognosis, not due to the direct involvement of EEF1A1 imparting anti-tumor activities, rather the correlation of its higher expression levels with lower levels of the proto-oncogenic isoform EEF1A2, thereby serving as a biomarker indirectly." (PMID 29342219, 2018). "Furthermore, qPCR results confirmed the microarray expression data of RGS1 and EEF1A1 in tumor ischemic colorectal tissue samples whereas differential expression of DUSP1, CYR61, SLC6A14 and DUOX2 in tumor ischemic colorectal tissue samples could not be validated." (PMID 26222051, 2015). "Also in the 22Rv1 cells, characterised by a growth rate comparable to LNCaP, the EEF1A1 mRNA levels did not significantly differ from those of PZHPV-7, whereas a significant (P=0.02) increase of EEF1A2 mRNA levels were found as in the other tumour cell lines tested." (PMID 22095224, 2012).
infection (29 papers, 2010 to 2025). The state of being infected such as from the introduction of a foreign agent such as serum, vaccine, antigenic substance or organism. "It was also recently demonstrated that the infection of macrophages with virulent Mycobacterium tuberculosis increases intracellular EBI3 expression via its binding to eukaryotic translation elongation factor 1-α1 (eEF1A1), probably to facilitate infection." (PMID 34603342, 2021).
adenocarcinoma (3 papers, 2018 to 2022). A common cancer characterized by the presence of malignant glandular cells. "Higher EEF1A1 levels in adenocarcinoma correlated with better OS and FP, while higher EEF1A2 levels predicted worse OS and FP." (PMID 29342219, 2018).
neurological disorders (3 papers, 2016 to 2025). "Additionally, while no studies directly related to ALS were discovered, other studies related to other neurological diseases were found in the cases of the EEF1A1, COX5A and RPL12 and RPL15 genes." (PMID 38540795, 2024).
neurodegenerative disease (2 papers, 2014 to 2021). A disorder of the central nervous system characterized by gradual and progressive loss of neural tissue and neurologic function. "Dysregulation of EEF1A1 is involved in the molecular mechanisms behind neurodegenerative diseases, which feature the presence of misfolded polypeptide-containing intracellular inclusion bodies." (PMID 34502537, 2021). "Our findings also suggest a novel therapeutic strategy for these neurodegenerative diseases by enabling eEF1A1 expression in motor neurons." (PMID 25233275, 2014).
psychiatric diseases (1 paper, 2011). "Taken together, it is likely that eEF1A families including eEF1A1 play a role in neurite outgrowth, indicating that eEF1A1 may be a potential target for developing therapeutic drugs for certain neurodegenerative and psychiatric diseases." (PMID 21390260, 2011).
EEF1A1 also shares sentences with these, for which no sentence is quoted: multiple myeloma (5 papers); Immunodeficiency (4); legionellosis (3); benign prostatic hyperplasia (2); fungal infection (2); leishmaniasis (2); leukemia (2); mandibulofacial dysostosis (2); mastitis (2); microcephaly (2); schizophrenia (2); achondroplasia (1); advanced heart failure (1); asthma (1); atrophic gastritis (1); bacteremia (1); bacterial disease (1); benign neoplasm (1); bipolar affective disorder (1); bladder carcinoma (1); bladder tumor (1); brain injury (1); brain tumors (1); bronchiectasis (1); Cerebellar atrophy (1); chronic pancreatitis (1); colitis (1); colonic adenoma (1); cystic fibrosis (1); demyelinating disorders (1).
A further 45 diseases each share a sentence with EEF1A1 in 1 paper.